INS (insulin)
Diseases named in the same sentence as INS in open-access papers (continued):
Sharing a sentence is not in itself a finding about the gene and the disease.
Insulin resistance (continued). "In contrast, and in agreement with previous reports, levels of IL-18 were found to be significantly increased among CWO displaying insulin resistance and were positively correlated with levels of obesity but not insulin sensitivity." (PMID 38467728, 2024). "Insulin does not directly affect GI motility, but high levels of insulin, as seen in conditions like insulin resistance, can slow gastric emptying." (PMID 38579770, 2024). "Moreover, metformin’s ability to enhance insulin sensitivity and reduce hyperglycemia is particularly relevant in HCV patients who exhibit insulin resistance." (PMID 39772244, 2024). "Insulin resistance (IR) plays a critical role in the development and progression of T2DM and is defined as a condition where insulin secretion remains normal, but the ability of tissues, organs, and cells to respond to insulin is diminished." (PMID 39545717, 2024). "Meanwhile, insulin tolerance tests (ITTs) indicated no insulin resistance and diminished insulin secretion upon glucose challenge compared with WT mice." (PMID 38731926, 2024). "Beyond effects on eicosanoids, cereal intake could also improve insulin sensitivity through these PUFA-containing phosphatidylcholines, which may help preserve bone mass since insulin resistance promotes osteoporosis." (PMID 39421617, 2024). "Since the aberrant lipolysis is induced before insulin resistance in YG8R mice, we wonder if enhanced lipolysis could improve insulin sensitivity." (PMID 39191875, 2024). "The insulin tolerance test (ITT) showed that RvE1 alleviated the insulin resistance of mice fed the HFD which showed no significance in Ucp1−/− mice." (PMID 38933207, 2024). "Since we found worsening of insulin and insulin resistance in CHR, most of whom do not develop psychosis, it would support the view that worsening of glucose metabolism is more commonly related to non-psychotic mental illness progression." (PMID 39085221, 2024). "Obesity is a major factor responsible for insulin resistance and leads to T2DM; because of insulin receptor (IR), three crucial insulin-responsive tissues such as the liver, skeletal muscle, and adipose tissues become insulin insensitive." (PMID 39759127, 2024). "The results showed that short-term insulin treatment improved glucose intolerance and insulin resistance without affecting body weight or gWAT weight in these mice compared with the control HFD group." (PMID 38816549, 2024). "High-fat fed adipocyte-specific Irf3 deficient (FI3KO) mice studied at thermoneutrality exhibit improved insulin and glucose tolerance, while adipocyte-specific overexpression of Irf3 (FI3OE) promotes glucose intolerance and insulin resistance on HFD, also in a weight-independent manner." (PMID 38816388, 2024). "SBP had positive correlations with obesity parameters, leptin, insulin, and insulin resistance but had a negative correlation with insulin sensitivity." (PMID 39285220, 2024). "Additionally, results from the glucose tolerance test (GTT) and insulin tolerance test (ITT) indicated that intestine‐specific NSD2 knockout ameliorated HFCD‐induced glucose intolerance and insulin resistance." (PMID 38923875, 2024). "In addition to stimulation of insulin or GLP‐1 secretion, approaches for improvement of insulin resistance are equally important." (PMID 38751366, 2024). "Research conducted on animals indicates that insulin resistance can be induced by transgenic over-expression of human RBP4 or injection of recombinant RBP4 into wild-type mice; conversely, deletion of the RBP4 gene results in increased insulin sensitivity." (PMID 38732128, 2024). "Notably, in mice studies, GH secretagogue receptor suppression in adipose tissues protects against obesity and insulin resistance, whereas IGF-I increases skeletal muscle insulin sensitivity." (PMID 39665021, 2024).
Insulin resistance (continued). "The widely used HOMA-IR index, which assesses β-cell function and insulin resistance, has limited value in patients undergoing insulin therapy or those without functional β-cells, and serum insulin measurement is not widely used in clinical practice." (PMID 39466812, 2024). "Insulin tolerance test results (insulin: 0.75 unit/kg) revealed no signs of insulin resistance in both sexes, despite the observed effects on glucose tolerance in male mice." (PMID 39639385, 2024). "The progress of diet-induced obesity, insulin resistance, or glucose intolerance was monitored by body weight, fasting or non-fasting blood glucose levels, insulin tolerance test (ITT), and oral glucose tolerance test (OGTT)." (PMID 39567934, 2024). "GB1107 improved glucose tolerance and insulin resistance, with enhanced insulin secretion but no change in body weight." (PMID 38693121, 2024). "Furthermore, the PD group had a significantly (p < 0.0001) higher HOMA-IR value compared to the NPD group, which was within the range of significant insulin resistance (>2.9), whereas the NPD group’s HOMA-IR value was within the insulin-sensitive range (1.0)." (PMID 38612885, 2024). "In contrast, rapamycin treatment in C57BL/6 mice resulted in insulin resistance, insulin sensitivity was not significantly affected by 4 weeks or 3 months of rapamycin treatment in 6- or 21-month-old HET3 mice." (PMID 38360109, 2024). "Deficits in insulin signaling, due to a lack of insulin in type 1 and insulin resistance in type 2 DM, can lead to a drop in neurotrophic pathway activation and neuronal deterioration." (PMID 39194903, 2024). "Insulin resistance, hyperinsulinemia, and type 2 diabetes are characterized by insulin resistance, a condition in which the body’s cells do not respond effectively to insulin." (PMID 38666802, 2024). "Insulin resistance is defined as the requirement for intravenous regular insulin infusion of more than 20 units/h without the ability to achieve appropriate serum glucose level (120–180 mg /dL)." (PMID 38365663, 2024). "In central tissues, KATP channels are activated by insulin, and the disruption of this pathway (by IR or PI3K inhibition) leads to peripheral or central insulin resistance; therefore, KATP channel activation protects against insulin resistance, while KATP channel inhibition promotes it." (PMID 38612888, 2024). "KITT(iv) is an index of insulin resistance that can be applied in clinical practice; along with HOMA-IR, it may be useful for efficiently adjusting insulin doses." (PMID 38905235, 2024). "This suggests that the mechanism by which QWBZS ameliorates insulin resistance may be related to the activation of the AMPK/PI3K/Akt signaling pathway and the enhancement of cellular sensitivity to insulin." (PMID 39845797, 2024). "To avoid systemic effects of Pfkfb3 overexpression we studied cultured L6-GLUT4-HA myotubes, which display robust insulin regulation of GLUT4 trafficking and develop insulin resistance upon palmitate treatment, mimicking lipotoxicity, a trigger of in vivo insulin resistance." (PMID 38329473, 2024). "A key metabolic disruption in obesity is insulin resistance (IR), a condition where the body’s cells do not respond effectively to insulin, resulting in elevated blood glucose and insulin levels." (PMID 39444570, 2024). "Although the BCS of riding horses did not increase with aging, they showed symptoms of insulin resistance, including increases in both plasma insulin and TG." (PMID 38881783, 2024). "Meta-analyses of randomized clinical trials (RCTs) investigating the effects of cinnamon on glycemic indices including fasting plasma glucose (FPG), homeostatic model assessment for insulin resistance (HOMA-IR), insulin, and hemoglobin A1C (HbA1c) were included." (PMID 37316893, 2023).
Insulin resistance (continued). "Insulin-stimulated TUG cleavage and expression of the putative protease Usp25m were reduced in rat adipose tissue after a 3-day high-fat/high-sugar diet-induced insulin resistance, suggesting possible dysregulation in insulin resistance." (PMID 37073948, 2023). "Focusing on insulin values and basal glycemia, neither males nor females developed insulin resistance (IR)." (PMID 37891887, 2023). "Sarcopenia promotes insulin resistance independent of obesity, since skeletal muscle is the major tissue involved in insulin-mediated glucose disposal." (PMID 36839249, 2023). "Children with a late insulin response, exhibit lower levels of high-density lipoprotein cholesterol (HDL-C), higher ratio triglycerides/HDL-C, higher uric acid levels and a higher homeostatic model assessment of insulin resistance (HOMA-IR)." (PMID 37599368, 2023). "Only patients with insufficient insulin response developed hyperglycemia, indicating that beta cell dysfunction, rather than insulin resistance, was responsible for its occurrence." (PMID 37460458, 2023). "Two‐week oral administration of compound‐1 dose‐dependently and significantly reduced changes in the levels of glycosylated hemoglobin (GHb), plasma glucose, plasma insulin, and HOMA‐IR in male KK‐Ay/Ta Jcl mice (KK‐Ay mice), a model of obese type 2 diabetes with severe insulin resistance." (PMID 36585794, 2023). "Therefore, we aimed to explore the possibility of using fibroblast growth factor 21 (FGF-21), free fatty acids (FFAs), homeostatic model assessment for insulin resistance (HOMA-IR), and quantitative insulin sensitivity check index (QUICKI) as possible markers." (PMID 38222178, 2023). "Then, to further explore the underlying mechanism by which NLRP3 inflammasome activation affects insulin resistance, we detected the expression and distribution of the IR-AKT-AS160 insulin signaling pathway-related proteins in NTg, NTg + CY-09, 3×Tg-AD, and 3×Tg-AD + CY-09 mice." (PMID 36978970, 2023). "Insulin resistance is clinically defined as a condition where known amount of exogenous or endogenous insulin fails to increase glucose uptake and utilization as much as in a normal population." (PMID 37434784, 2023). "Thus, instead of being triggered by insulin resistance, PCOS should alternatively be considered as a syndrome of ovarian “hypersensitivity” to insulin." (PMID 37047265, 2023). "No change was observed between the groups for BMI, insulin, or the Homeostasis Model Assessment for Insulin Resistance (HOMA) index." (PMID 37239916, 2023). "Additionally, we discovered in this study that QUER treatment resulted in a considerable drop in blood insulin levels in PCOS mice, suggesting a potential function for QUER in the treatment of insulin resistance." (PMID 37670876, 2023). "Meanwhile, comparison 2 showed that insulin resistance, type II diabetes mellitus, the pentose phosphate pathway, the AMPK signaling pathway, arginine and proline metabolism, and insulin secretion were upregulated, while only the melanogenesis pathway was downregulated in the T2D + OMV group." (PMID 37649633, 2023). "Aberrant insulin action in the liver is a major driver of selective insulin resistance, in which insulin fails to suppress glucose production but continues to activate lipogenesis in the liver, resulting in hyperglycemia and hypertriglyceridemia." (PMID 37088778, 2023). "Because of the insulin resistance, DM2 is also referred as insulin-independent DM type." (PMID 37790608, 2023). "Furthermore, the patient exhibited a fasting insulin level of >20 mU/L, with insulin levels soaring to 458.5 mU/L 2 hours after glucose intake, and a HOMA-IR of 8.84, signifying a notable degree of insulin resistance." (PMID 38333726, 2023). "The hyperinsulinemia observed in animals without insulin resistance correlated to a strong ITT response suggesting a stimulation of insulin release by the Asteraceae infusion-drink." (PMID 36829899, 2023).
Insulin resistance (continued). "While IFG may be due to impaired early insulin secretion and increased hepatic glucose output, IGT is mainly due to peripheral insulin resistance." (PMID 37064311, 2023). "Individuals with obesity and insulin resistance display increased ECM deposition in adipose tissue compared to those with obesity of equivalent BMI and normal insulin sensitivity, implying that abnormal ECM remodelling is crucial in the pathophysiology of insulin resistance." (PMID 37383542, 2023). "To exclude that improved glucose tolerance in HFD-fed LMKO mice was the consequence of altered insulin resistance, rather than improved gluconeogenesis, we performed intraperitoneal insulin tolerance tests (IP-ITT)." (PMID 38123539, 2023). "In teenage females with PCOS, yoga was found to be more beneficial than traditional physical activity in improving glucose, insulin, and lipid levels, including insulin resistance values, irrespective of anthropometric changes." (PMID 37383339, 2023). "In a fructose-fed hamster model of insulin resistance, a study found cellular changes in the insulin receptor signaling pathway as well as a lack of sensitivity to insulin-induced downregulation of CM secretion." (PMID 38303975, 2023). "The close relationship observed between insulin resistance and NAFLD is confirmed by elevated free fatty acid levels during fasting and a reduced suppression of lipolysis after insulin administration, which strongly correlate with the degree of fatty infiltration of the liver." (PMID 37371817, 2023). "Compromised insulin secretion rather than insulin resistance seems to be the primary defect, but this needs to be determined in larger and/or methodologically more sophisticated studies." (PMID 37333553, 2023). "Phosphoproteomics has revolutionised our understanding of the signalling changes occurring in insulin resistance, revealing complex rearrangements rather than simple defects in insulin signalling." (PMID 37248992, 2023). "Insulin resistance is an important driver of metabolic disease, yet the molecular changes in insulin signalling and/or GLUT4 traffic that confer insulin resistance remain largely unknown." (PMID 37248992, 2023). "Whilst T1DM is caused by an absolute lack of insulin on an autoimmune or idiopathic basis, T2DM is characterized by the presence of insulin resistance and relative insulin deficiency." (PMID 37111385, 2023). "In another study, serum BPA levels showed a positive relationship with blood glucose and insulin levels and HOMA-insulin resistance in the middle term of pregnancy; an increased BPA concentration tended to increase the risk ratio of GDM, although this was not statistically significant." (PMID 38132710, 2023). "Contrary to adipocytes cultured separately, adipocytes cocultured with macrophages failed to enhance glucose uptake in response to insulin, which indicates that the coculture induced insulin resistance." (PMID 36834930, 2023). "The observed beneficial effects of a ketogenic diet in T2DM are the reduction and stabilization of glucose and insulin concentrations in serum, the reduction of glycated hemoglobin concentration, and the reduction of the HOMAR-IR indicator, insulin resistance, and body mass." (PMID 36771207, 2023). "If the pancreatic beta-cells are able to overcome insulin resistance by increasing their insulin secretory response, frank type 2 diabetes will not occur." (PMID 36901984, 2023). "Gremlin-1 has been found to be involved in adipose tissue dysfunction and insulin resistance, antagonizes insulin action and is overexpressed in type 2 diabetes, obesity, non-alcoholic fatty liver disease (NAFLD) and in polycystic ovarian syndrome (PCOS)." (PMID 37518503, 2023).
Insulin resistance (continued). "Anthraquinones are believed to ameliorate insulin resistance through diverse pathways, encompassing activation of the AMP-activated protein kinase (AMPK) signaling pathway, restoration of insulin signal transduction, attenuation of inflammatory pathways, and modulation of gut microbiota." (PMID 38053837, 2023). "Many patients with obesity do not develop T2DM but adapt to chronic insulin resistance by increasing β-cell mass and insulin secretion." (PMID 36681689, 2023). "In comparison with the vehicle group, C. albicans significantly accelerated the features of T2D and insulin resistance in the HFD-fed mice, indicated by the increasing fasted blood glucose, HbA1c level and HOMA-IR, and the impairing insulin tolerance and glucose tolerance." (PMID 36854740, 2023). "INS and HOMA‐IR levels were elevated in the HFD group compared with the ND group (p < .05), suggesting that the high‐fat diet‐induced obese rats compensated for insulin secretion and possibly insulin resistance due to elevated glucose." (PMID 37181308, 2023). "There were no intervention effects on glucose, insulin, homeostatic model assessment of insulin resistance, or other lipid parameters." (PMID 36626172, 2023). "Overall, our findings imply that insulin resistance substantially rewires the insulin signaling network, and this is generally not due to equivalent changes in protein levels." (PMID 36808134, 2023). "In brief, the data we present do not indicate insulin resistance in the skeletal muscle, which supports that impaired insulin secretion rather than insulin resistance, explains the mild elevations of plasma glucose levels in the PPM+ group." (PMID 37333553, 2023). "Insulin resistance describes a condition whereby cells no longer respond appropriately to circulating insulin." (PMID 37763308, 2023). "Insulin resistance is a prime symptom of T2DM, where cells fail to respond to insulin." (PMID 37351102, 2023). "Five compounds both stimulated GLUT4 translocation and reversed insulin resistance, four were both basal agonists and insulin sensitisers while none met all three criteria." (PMID 37494090, 2023). "Like other authors, we have not observed FGF21 to be correlated with insulin levels when analyzing insulin resistance markers." (PMID 37869250, 2023). "Third, this study was not conducted HOMA-IR, the gold standard of insulin sensitivity evaluation, and was used as an alternative tool for identifying insulin resistance." (PMID 37273533, 2023). "Additionally, it has been discovered that, in first trimester overweight pregnant women, the genus Collinsella is positively correlated with insulin, c-peptide, and HOMA-IR (a marker of insulin resistance)." (PMID 37280680, 2023). "In insulin resistance, high insulin levels do not have the expected effect on glucose transport and blood sugar levels." (PMID 37239168, 2023). "Results showed that, in one hand PP1γ, and not PP1α, regulates neuronal insulin signaling and insulin resistance by regulating phosphorylation of AKT2 via AKT2-AS160-GLUT4 axis." (PMID 37085815, 2023). "The very first stage of hyperinsulinemia is when insulin is likely within normative population reference ranges with glucose and HbA1c also being normal, and therefore is not diagnosed as insulin resistance." (PMID 37760052, 2023). "Collectively, this analysis suggests impaired insulin-activation of ERK and CDK5 may contribute to insulin resistance." (PMID 36808134, 2023). "First, most of the insulin research in depression has specifically focused on insulin resistance as opposed to total insulin concentration as measured in the Tulsa 1000 project." (PMID 37443383, 2023). "Potential mechanisms may include hyperinsulinemia, insulin resistance, elevated IGF-I levels, oxidative stress, chronic inflammation, and anti-insulin medication use." (PMID 38020199, 2023).